DUSP13A (dual specificity phosphatase 13A)
Description:
Probable protein tyrosine phosphatase. Has phosphatase activity with synthetic substrates. Has a phosphatase activity-independent regulatory role in MAP3K5/ASK1-mediated apoptosis, preventing MAP3K5/ASK1 inhibition by AKT1. Shows no phosphatase activity on MAPK1/ERK2, MAPK8/JNK, MAPK14/p38 and MAP3K5/ASK1.
Synonyms: MDSP; BEDP; DUSP13
Tractability: No criterion of Open Targets' tractability assessment is met for any kind of drug.
Gene: Protein-coding gene on chromosome 10 (75,094,434 to 75,109,221, reverse strand). Ensembl gene ENSG00000293543.
Subcellular location: Cytoplasm
Gene Ontology:
Molecular function: phosphatase activity; protein serine/threonine phosphatase activity; protein tyrosine phosphatase activity; protein tyrosine/serine/threonine phosphatase activity
Biological process: dephosphorylation
Cellular component: cytoplasm
Homologues: Orthologues: mouse Dusp13a (86% identical), tropical clawed frog dusp13 (54% identical), zebrafish si:ch211-223p8.8 (53% identical). Paralogues in human: DUSP26 (54% identical), DUSP29 (49% identical), DUSP13B (44% identical), DUSP3 (40% identical), STYXL2 (38% identical), DUSP9 (33% identical), DUSP1 (32% identical), DUSP2 (32% identical), DUSP4 (32% identical), DUSP7 (31% identical), SSH3 (31% identical), DUSP14 (30% identical), and 19 more.